GSTM1 (glutathione S-transferase mu 1)
Diseases named in the same sentence as GSTM1 in open-access papers (continued):
Sharing a sentence is not in itself a finding about the gene and the disease.
rheumatoid arthritis (3 papers, 2010 to 2015). A chronic, systemic autoimmune disorder characterized by inflammation in the synovial membranes and articular surfaces. "Associations of GSTM1-null with ACPA positivity were examined separately in two RA cohorts, the Veterans Affairs Rheumatoid Arthritis (VARA) registry (n = 703) and the Study of New-Onset RA (SONORA; n = 610)." (PMID 21087494, 2010). "We aimed to investigate GSTM1 CNV in Rheumatoid Arthritis (RA) in relation to smoking and HLA-DRB1 shared epitope; the two best known risk factors for RA and in addition, to perform subanalyses in patients where relations between variations in GSTM1 and RA have previously been described." (PMID 21445357, 2011). "A deletion polymorphism in glutathione S-transferase Mu-1 (GSTM1-null) has previously been implicated to play a role in rheumatoid arthritis (RA) risk and progression, although no prior investigations have examined its associations with anticitrullinated protein antibody (ACPA) positivity." (PMID 21087494, 2010).
testicular cancer (3 papers, 2012 to 2020). A primary or metastatic malignant neoplasm that affects the testis. "For example, in a study involving 173 survivors of testicular cancer, genetic variants of glutathione S-transferase (GST) are described as a key determinant of cisplatin-induced ototoxicity: the GSTM1 polymorphism is described as detrimental and 105Val-GSTP1 described as protective." (PMID 22919381, 2012).
urothelial carcinoma (3 papers, 2011 to 2021). A malignant neoplasm derived from the transitional epithelium of the urinary tract (urinary bladder, ureter, urethra, or renal pelvis). "One is the GSTM1 gene which is down-regulated in mice bladder carcinogenesis and is usually deleted in human urothelial carcinoma, while the other is the GSTM5 gene, which is inactivated by DNA CpG methylation." (PMID 27404495, 2016).
varicocele (3 papers, 2015 to 2025). A condition characterized by the dilated tortuous veins of the spermatic cord with a marked left-sided predominance. "In Taiwanese patients with varicocele, subjects with GSTM1-null genotype had significantly higher 8-OHdG levels in sperm DNA and lower protein thiols and ascorbic acid in seminal plasma than those with the GSTM1+ genotype." (PMID 26618172, 2015).
acute chest syndrome (2 papers, 2022 to 2024). A vaso-occlusive crisis of the pulmonary vasculature occurring in patients with sickle cell disease. "It was demonstrated that the GSTM1 null genotype was associated with acute chest syndrome and veno-occlusive crisis, while the GSTT1 null genotype was associated with increased blood transfusion requirements." (PMID 38732015, 2024). "GSTM1 null genotypes had a high risk of developing malleolar ulcer, acute chest syndrome and femoral head aseptic necrosis." (PMID 36532755, 2022).
Age-related cataract (2 papers, 2015 to 2025). A type of cataract (opacification of the lens) that forms during the course of aging. "The GSTM1-positive genotype, as well as the combined “GSTM1-positive/GSTT1-positive" genotype, has been correlated with an elevated risk of developing senile cataracts in an Egyptian cohort." (PMID 40290119, 2025).
allergic disease (2 papers, 2019 to 2020). An immune response that occurs following re-exposure to an innocuous antigen, and that requires the presence of existing antibodies against that antigen. "Correlation of the CpG methylation levels of LMO2_P794, LMO2_E148, GSTM1_P266, and IL10_P325 to prenatal PTS and allergic diseases." (PMID 31214241, 2019).
aplastic anemia (2 papers, 2025). Anemia resulting from bone marrow failure (aplastic or hypoplastic bone marrow). "This implies an increased risk of aplastic anemia in patients with GSTM1 and GSTT1 gene knock outs." (PMID 41334396, 2025).
Atopic Dermatitis (2 papers, 2011 to 2015). "Association between dietary pattern and atopic dermatitis (AD) by of the glutathione S-transferase M1 (GSTM1) and /or T1 (GSTT1) genotypes (n = 438) *." (PMID 26580648, 2015). "The genetic polymorphisms in GSTM1 and GSTP1 may be responsible for differences in susceptibility to atopic dermatitis with regard to prenatal smoke exposure." (PMID 21838884, 2011).
Azoospermia (2 papers, 2015 to 2022). Absence of any measurable level of sperm,whereby spermatozoa cannot be observed even after centrifugation of the semen pellet. "The association of polymorphisms in GSTM1, GSTT1, and GSTP1 with idiopathic azoospermia or oligospermia was also observed in a southwest Chinese population." (PMID 26618172, 2015). "In a Chinese population, the null genotype of GSTM1 and GSTT1 is associated with an increased susceptibility to impaired spermatogenesis such as idiopathic azoospermia or oligospermia." (PMID 26618172, 2015).
basal cell carcinoma (2 papers, 1996 to 2007). A carcinoma involving the basal cells. "For example, GSTM1 null genotype was associated with cutaneous basal cell carcinoma and with solar keratoses." (PMID 18053222, 2007).
bladder (2 papers, 2016 to 2017). "By using BBN-induced mouse bladder carcinogenesis and protein 2D electrophoresis analysis, we found that mouse bladder glutathione S-transferase Mu1 (GSTM1) protein was down-regulated after BBN treatment." (PMID 27404495, 2016). "In our previous study, we found that the bladder carcinogen BBN increased urothelial global DNA CpG methylation and decreased GSTM1 protein expression in mice." (PMID 27404495, 2016).
cervical intraepithelial neoplasia (2 papers, 1994 to 2011). "Moreover, studies examining the association between GSTM1 and GSTT1 polymorphisms and cervical intraepithelial neoplasia were also selected." (PMID 21629772, 2011).
cholestasis (2 papers, 2015 to 2022). Impairment of the bile flow caused by obstruction within the liver, or outside the liver in the bile duct system. "Hepatic mRNA levels of GSTM1, GSTM2, and GSTM4 in patients with cholestasis were decreased to 38%, 46%, and 43% of control, respectively (p<0.05 for all), while GSTM3 and GSTM4 mRNA levels were not significantly changed." (PMID 25798860, 2015).
chronic lymphocytic leukemia (2 papers, 2019 to 2024). "Yuille and co-workers studied the relationship between genotypes of GSTM1, GSTT1, GSTP1, and chronic lymphocytic leukemia (CLL)." (PMID 31681592, 2019).
chronic rhinosinusitis (2 papers, 2019 to 2024). Chronic form of sinusitis. "There is statistical correlation between the polymorphisms of the GSTT1, GSTM1, and GSTP1 genes and the genetic tendency of chronic rhinosinusitis with or without nasal polyps in Germany." (PMID 30617052, 2019).
colorectal tumours (2 papers, 2003 to 2023). "were associated with prevention/protection against large intestine neoplasms, including GUCA2A, CDX2, VDR, VEFGA, GSTM1, HPGD, and PPARG." (PMID 37296943, 2023). "Furthermore, TTI-101 treatment also led to the upregulation of important genes such as GUCA2A, CDX2, VDR, GSTM1, HPGD, and PPARG that have been shown by others to be associated with the prevention of large intestine neoplasms." (PMID 37296943, 2023).
diabetic nephropathy (2 papers, 2015 to 2023). "The present study was designed to investigate the possible modifying effect of glutathione transferase polymorphisms (GSTM1, GSTT1, GSTP1 rs1138272/rs1695, GSTO1 rs4925 and GSTO2 rs156697) in the susceptibility to T2DM and diabetic nephropathy." (PMID 36676788, 2023). "Hence, the present study was designed to investigate the possible modifying effect of GSTs polymorphisms (GSTM1, GSTT1, GSTP1, GSTO1 and GSTO2) in the susceptibility to T2DM and diabetic nephropathy as its major microvascular complication." (PMID 36676788, 2023). "Also, the carriers of both GSTM1 null and GSTT1 null genotypes, resulting in a complete lack of enzyme activity, did not have an increased risk for developing DR or diabetic nephropathy." (PMID 26435566, 2015).
female infertility (2 papers, 2023). Diminished or absent ability of a female to achieve conception. "Grouping CYP19A1 and GSTM1 genotypes, female infertility susceptibility was altered until when GSTM1 was present, as well as for carriers of GSTM1 null plus CYP19A1 C allele." (PMID 37107315, 2023). "The aim of this study is to investigate the effect of the GSTM1-null polymorphism in female infertility as well as in IVF parameters." (PMID 38068321, 2023). "Several studies reveal a possible correlation between female infertility and GSTM1 polymorphisms." (PMID 38068321, 2023). "This case-control study was performed to assess the potential role of CYP19A1, GSTM1, and GSTT1 in modifying individual predisposition to female infertility." (PMID 37107315, 2023). "As far as we know, these are the first published results regarding the potential role of CYP19A1 codon 39 polymorphism and its potential effect together with GSTM1 and GSTT1 in the development of female infertility." (PMID 37107315, 2023). "To validate this premise, we conducted a case-control study to assess the putative role of CYP19A1, GSTM1, and GSTT1 in the modulation of individual predisposition to female infertility." (PMID 37107315, 2023). "The combined analysis of CYP19A1, GSTM1, and GSTT1 polymorphisms showed an association with female infertility risk for carriers of GSTM1 and GSTT1 present genotype (OR 7.108; 95% CI (2.777–18.197; p < 0.001)." (PMID 37107315, 2023). "The combination of all presumed high-risk genotypes, CYP19A1 TC/CC, GSTM1 deletion, and GST11 deletion, refers to a statistically significant association with female infertility risk (OR 47.914; 95% CI (14.051–163.393; p < 0.001)." (PMID 37107315, 2023). "Additionally, when GSTM1 and GSTT1 are deleted, there is a significant association with the risk of female infertility; this risk is independent of the CYP19A1 genotype." (PMID 37107315, 2023).
Hepatic steatosis (2 papers, 2022 to 2024). Steatosis is a term used to denote lipid accumulation within hepatocytes. "GSTM1 loss robustly aggravated alcohol-induced hepatic steatosis, oxidative stress, inflammation, and early fibrotic-like changes, which was associated with the activation of apoptosis signal-regulating kinase 1 (ASK1), c-Jun N-terminal kinase (JNK), and p38." (PMID 38475733, 2024). "Down-regulation of miR-743a-3p improves alcohol intake-induced hepatic steatosis and liver injury via direct targeting on GSTM1." (PMID 38475733, 2024).
inflammatory bowel disease (2 papers, 2019 to 2020). A spectrum of small and large bowel inflammatory diseases of unknown etiology. "A significant association was found between GSTM1 null genotype and GSTT1 gene polymorphism in inflammatory bowel diseases." (PMID 33083304, 2020).
iron overload (2 papers, 2016 to 2019). "We evaluated the association of the copy number of the glutathione S-transferase M1 (GSTM1) gene and degree of iron overload among patients with SCA." (PMID 31694285, 2019).
larynx cancer (2 papers, 2020 to 2022). A primary or metastatic malignant neoplasm involving the larynx. "As results patients with larynx cancer present more gene GSTM1 and GSTT1 null polymorphisms, and CYP1A1 rs4646903 T>C polymorphisms." (PMID 32882964, 2020). "Conclusions: patients with larynx cancer present more gene GSTM1 and GSTT1 null polymorphisms, and CYP1A1 rs4646903 T>C polymorphisms." (PMID 32882964, 2020). "The present results are similar to those of other authors who have also demonstrated an increased risk of larynx cancer in individuals with null GSTM1 genotype." (PMID 32882964, 2020). "The findings for larynx cancer have shown that GSTM1 null polymorphism cancels the enzyme’s function, which is associated with the development of larynx cancer." (PMID 32882964, 2020). "The aim of this study was to determine the presence of SNPs responsible for the loss of function of GSST1, GSTM1, CYP1A1 and CYP1A2 genes, as markers of risk, in a group of smokers and drinkers with larynx cancer." (PMID 32882964, 2020). "Objective: to compare the presence of null SNPs in genes GSTM1, GSTT1, and CYP1A1 rs 4646903 T>C, and CYP1A1–2 RS1048943 A>G in patients with hypopharyngeal and larynx cancer with a healthy control group." (PMID 32882964, 2020).
leiomyoma (2 papers, 2013 to 2016). A well-circumscribed benign smooth muscle neoplasm characterized by the presence of spindle cells with cigar-shaped nuclei, interlacing fascicles, and a whorled pattern. "Although, with small numbers in each group of this study, we have a consistent and significant result showing that the leiomyoma volume reduction is associated with GSTM1 expression." (PMID 24324590, 2013). "In connection to our finding of 50% gene polymorphism, an earlier report that GSTM1 deleted phenotype has an association with increased risk for leiomyoma develoment." (PMID 24324590, 2013). "Correlation of immunoreactive scores (IRS) for GSTM1 accumulation in leiomyoma tissue was seen with base line volume change of leiomyoma R = −0.8 (p = 0.011)." (PMID 24324590, 2013). "GSTM 1 expression leiomyoma volume reduction: Comparison of GSTM1 expression as seen by by real time PCR and Western Blot in relation to percentage of leiomyoma volume change during 3 months of mifepristone treatment." (PMID 24324590, 2013). "By categorisation according to GSTM1 deletion or not, there were significant differences between categories in IRSGSTM1 (N = 8) score both in leiomyoma smooth muscle cell bundles (p = 0.030) and matrix (p = 0.030) of GSTM1+." (PMID 24324590, 2013). "Data for leiomyoma volume reduction as well as protein accumulation were analysed and categorised according to the expression of GSTM1 gene by MLPA analysis." (PMID 24324590, 2013). "We demonstrated a good correlation in leiomyoma volume reduction in response to mifeprsitone with the expression of GSTM1 in the tissue." (PMID 24324590, 2013). "Deletion of the GSTM1 gene in leiomyoma biopsies was found in 50% of the mifepristone treated cases, with lower presence of the GSTM1 protein." (PMID 24324590, 2013). "The findings support a significant role for GSTM1 in leiomyoma volume reduction induced by mifepristone and explain the observed individual variation in this response." (PMID 24324590, 2013). "The role of GSTM1 in leiomyoma could be related to cell-cycle or metabolic events through regulatory metabolism of the steroid hormone receptor and its ligands." (PMID 24324590, 2013). "Furthermore the accumulation of protein GSTM1 analysed by Western Blot correlated significantly with the percentual leiomyoma volume change R = −0.82 (p = 0.004)." (PMID 24324590, 2013). "The negative correlation between GSTM1 protein accumulation and leiomyoma volume change was highly significant assessing 10 mifepristone treated cases, R = −0.82 (p = 0.004)." (PMID 24324590, 2013). "Two cases were lacking data for GSTM1 copy number, as it was not possible to obtain sufficient remaining leiomyoma tissue." (PMID 24324590, 2013).
Lynch syndrome (2 papers, 2021 to 2022). An autosomal dominant hereditary neoplastic syndrome characterized by the development of colorectal carcinoma and a high risk of developing endometrial carcinoma, gastric carcinoma, ovarian carcinoma, renal pelvis carcinoma, and small intestinal carcinoma. "A predisposing mutation for Lynch syndrome is Glutathione S-Transferase Mu 1 (GSTM1)-null mutation, which is also correlated with interleukin gene expression mainly for IL-10 and IL17." (PMID 34947835, 2021).
meningioma (2 papers, 2010 to 2024). A generally slow growing tumor attached to the dura mater. "Another DEG upregulated in GSTM1- meningiomas compared to GSTM1+ tumors is NEDD4, which encodes a member of HECT family of E3 ubiquitin ligases." (PMID 39726707, 2024). "Since measuring GSTM1 expression in additional tumor subtypes will allow us to determine if it is a common biomarker for recurrent meningiomas, we plan to analyze 14q-22q- and other subtypes of meningiomas in our future follow-up studies." (PMID 39726707, 2024). "This also aligns with the observation that GSTM1- meningiomas had significantly lower GSTM2 expression versus GSTM1+ meningiomas." (PMID 39726707, 2024). "There were 516 DEGs upregulated and 499 downregulated in GSTM1- meningiomas and the primary tumors with GSTM1 expression showed a trend towards clustering together." (PMID 39726707, 2024). "The expression of GSTM1 on chromosome 1p13 is downregulated in recurrent 1p-22q-NF2- meningiomas leading to a GSTM1 null genotype." (PMID 39726707, 2024). "Accordingly, recurrent meningiomas have inactivation of both copies of the gene either due to GSTM1 or 1p13 deletions." (PMID 39726707, 2024). "Future experiments are needed to examine the existence of a significant relationship between GSTM1 copy numbers and meningioma development." (PMID 39726707, 2024). "It will be important for future studies to further evaluate these additional pathways and DEGs to identify potential additional biomarkers of meningioma progression beyond GSTM1 as well as potential novel therapeutic targets." (PMID 39726707, 2024). "Recurrent 1p-22q-NF2- meningiomas were enriched for a newly identified GSTM1 null genotype compared to primary meningiomas that showed variable GSTM1 expression and independent external validation was performed." (PMID 39726707, 2024). "This study identifies GSTM1 as a new biomarker of meningioma recurrence that builds on existing molecular subtypes to improve our ability to predict and manage recurrent meningiomas." (PMID 39726707, 2024). "The association of GSTM1 and GSTT1 genetic polymorphism with the development of meningiomas has been previously examined." (PMID 39726707, 2024). "While this model is partially supported by the increases in MAP1LC3C and NEDD4 expression in the GSTM1- meningiomas, future studies will be needed to investigate the various components of this model at both the mRNA and protein level." (PMID 39726707, 2024). "Gene set enrichment analyses revealed that pathways upregulated in GSTM1- meningiomas were related to cell-to-cell interaction and angiogenesis while downregulated pathways were related to transmembrane transport and intracellular signaling." (PMID 39726707, 2024). "Another difference between the studies was that the majority of meningiomas in our group with GSTM1 null genotype had only one copy of the gene lost due to inherited deletion of the gene, while another copy may have been lost due to somatic chr1p deletion." (PMID 39726707, 2024). "With the availability of public datasets in the gene expression omnibus (GEO), we evaluated meningioma expression studies to determine if we could find evidence of GSTM1 under expression in recurrent meningiomas." (PMID 39726707, 2024). "All meningiomas with GSTM1 under expression also showed copy number losses of GSTM1." (PMID 39726707, 2024). "No meningiomas were homozygous for the wild type allele of GSTM1 (variant E) or had both GSTM1 and GSTM2 somatic deletions (variant F)." (PMID 39726707, 2024). "The GSTM1 null genotype is a novel biomarker of 1p-22q-NF2- meningioma recurrence that resolves heterogeneity in existing meningioma subtypes and may be used to guide future clinical management decisions on extent of treatment to improve patient outcomes." (PMID 39726707, 2024).